GSDMD (gasdermin D)
Diseases named in the same sentence as GSDMD in open-access papers (continued):
Sharing a sentence is not in itself a finding about the gene and the disease.
tumor (continued). "Protrusions facilitate lysosomal rupture, following which the tumor overexpressed glutathione (GSH) triggers the degradation of VPTA to release Mn ions and IONPs for rapid and persistent ROS generation, which synergistically activates the NLRP3/caspase-1/GSDMD signaling pathway for pyroptosis." (PMID 35673561, 2022). "As GSDMD-mediated pyroptosis promotes tumor infiltration and activation of CD8+ T lymphocytes, we, therefore, speculated that GSDMD-dependent pyroptosis will synergize with immune checkpoint blockage therapies to potentiate anti-tumor immunity." (PMID 36323669, 2022). "Compared to the controls that received vector cells with induction or GSDMD-NT cells without induction, the induction of pyroptosis in GSDMD-NT cells significantly reduced the size and the weight of the isolated tumor masses, and the weight of the spleen." (PMID 36189310, 2022). "Therefore, the MEG3/NLRP3/caspase-1/GSDMD pathway may be one of the important mechanisms for DDP to induce pyroptosis and exert anti-tumor effects in TNBC." (PMID 34326697, 2021). "Notably, the activation of NLRP3/caspase-1 signaling induces apoptosis rather than pyroptosis in tumor cells lacking GSDMD." (PMID 31501419, 2019). "Interestingly, in contrast to the reported mechanisms inducing pyroptosis in tumor cells,[23c] we found that granzyme B may induce hepatocyte pyroptosis by acting on GSDMD but not GSDME." (PMID 39494472, 2025). "Similarly, during cisplatin chemotherapy, GSDMD overexpression has been found to increase phosphorylation of eukaryotic translation initiation factor 2 alpha (eIF2α), activating the ER stress response and promoting tumor cell apoptosis rather than pyroptosis." (PMID 40783818, 2025). "Metformin and Compound C, together with other GSDMD-targeted chemicals including Necrosulfonamide (NSA), disulfiram and Dimethylformamide (DMF), may promote the development of pharmaceutical strategies to improve the outcomes of tumor and inflammatory diseases." (PMID 37495617, 2023). "During cell pyroptosis, the activated N-terminal GSDMD proteins would insert into the cell membrane to form the pore, and eventually the cells rupture to release the inside contents, which could result in elevated lactate dehydrogenase (LDH) released from tumor cells." (PMID 36280674, 2022). "In murine tumor models, DMB-induced low-level pyroptosis suppresses tumor growth without impairing the function of immune cells expressing GSDMD." (PMID 39994107, 2025). "Unlike traditional pathways requiring GSDMD cleavage, DMB induces pyroptosis without this step, effectively stimulating anti-tumor immune responses with minimal toxicity." (PMID 39587093, 2024). "The lack of GSDMD also had no significant impact on immune populations in the spleen of tumor-bearing mice or on the phenotype of CD4+ and CD8+ T cells in the tumor-draining lymph nodes." (PMID 39224600, 2024). "Meanwhile, the mRNA and protein expression levels of NLRP3, caspase 1, GSDMD, IL-1β and IL-18 in H(FMT) group were higher than that in T(FMT) group, while there were no noticeable difference between T(FMT) group and tumor model group." (PMID 40046008, 2024). "Not surprisingly, the high expressions of GSDMA, GSDMC, GSDMD and GSDME were observed correlated with low tumor purity." (PMID 35164740, 2022). "Therefore, for the first time, our work reveals an unreported nonpyroptotic function of the classic pyroptosis protein GSDMD: it promotes cell apoptosis during cisplatin chemotherapy by inducing eIF2α phosphorylation and ER stress, which are related to the drug sensitivity of tumours." (PMID 35289335, 2022). "In addition, the IHC results implied a negative correlation of cleaved-GSDMD staining score with the LINC01133 score in patient PAAD tissues and subcutaneous tumor tissues." (PMID 37138146, 2023). "Unlike GSDMD, GSDME has been reported as a tumor suppressor in several studies." (PMID 31616642, 2019).
tumor (continued). "This subsequently triggers absent in melanoma 2 (AIM2)/caspase‐1/gasdermin D (GSDMD)‐mediated pyroptosis, thereby enhancing tumor immunity and the efficacy of anti‐PD‐L1 immunotherapy in both microsatellite instable (MSI) and microsatellite stable (MSS) tumor cells." (PMID 39903759, 2025). "A mechanistic study revealed that GSDMD was involved in regulating OSCC metastasis through a novel mechanism involving interactions with MMP14 to upregulate MMP14 expression, thereby mediating the tumor EMT process and inducing OSCC metastasis without activating the classical pyroptosis process." (PMID 40178046, 2025). "Notably, GSDMD knockout did not completely inhibit the production of IL-6, tumor TNF-α, and IL-10, suggesting that GSDMD-independent pathways may contribute to inflammation." (PMID 41345109, 2025). "Therefore, this study aimed to assess the ability of live recombinant L. monocytogenes to stimulate CD8+ T cell-mediated anti-tumor immunity in animal models lacking the essential regulatory and effector molecules of necroptosis (RIPK3 and MLKL) and pyroptosis (caspase 1/11 and Gasdermin D (GSDMD))." (PMID 39452700, 2024).
infection (247 papers, 2017 to 2026). The state of being infected such as from the introduction of a foreign agent such as serum, vaccine, antigenic substance or organism. "We found that GSDMD deficient animals (Gsdmd–/–) showed similar viral burden and weight loss compared to WT mice upon infection with SARS-CoV-2 P21." (PMID 40016339, 2025). "GSDMD is a downstream effector of NLRC4 and, like NLRC4-deficiency, GSDMD-deficiency in mice leads to the collapse of the epithelial barrier after 72 h of S. TmWT infection." (PMID 41370284, 2025). "In the antibacterial and antiviral processes, bacteria and inflammasomes can cause cleavage of GSDMD by activating caspases, thereby inducing pyroptosis, which can eliminate pathogens and prevent infection." (PMID 40704967, 2025). "For example, caspase-1/4/5/8/11 are known to cleave GSDMD, which results in GSDMD-mediated pyroptosis, and under pathogenic infection, caspase-1 cleavage of GSDMD is the most common occurrence of GSDMD-mediated pyroptosis." (PMID 40503916, 2025). "Gasdermin D is a critical protein involved in the execution of pyroptosis, an infection-induced inflammatory cell death process associated with immune response regulation." (PMID 40563885, 2025). "Next, the cleavage of GSDMD (gasdermin D) by caspase 1 and caspase 11 to produce the N-terminal fragment of GSDMD (N-GSDMD) is a critical event in the lethal cascade driving infection-associated pyroptotic cell death." (PMID 39587094, 2024). "Gsdmd−/− mice lost significantly less weight than their WT counterparts, though it is important to note that the sickest WT mice succumbed to infection, masking the full extent of the protective benefits of GSDMD deficiency at later timepoints." (PMID 38553499, 2024). "We now show that infection of caspase-1 or gasdermin D deficient macrophages by this flagellin-engineered S. Typhimurium induces apoptosis in vitro." (PMID 38055781, 2023). "GSDMD-deficient mice feature elevated organ pathogen loads during infections with the lung pathogen Burkholderia cenocepacia." (PMID 37988464, 2023). "Similar observations were made in 48-h infections, or in BM chimeric mice derived from GSDMD-deficient recipients, which were infected for 48 h or 96 h." (PMID 37988464, 2023). "Gasdermin D is released after activation of the inflammasome by pathogen- and danger-associated molecular patterns (PAMPs and DAMPs) in the context of infection and/or injury." (PMID 37373482, 2023). "Following infection by Escherichia coli (E. coli), GSDMD deficiency enhances antimicrobial activity by increasing neutrophil survival." (PMID 35677444, 2022). "Mice with GSDMD-deficient BMDMs are more vulnerable to Francisella novicida (F. novicida, intracellular bacteria) infection than WT mice." (PMID 35677444, 2022). "Since GSDMD has been reported as a key effector for pyroptosis, many studies had been performed on human and murine GSDMD, but studies focusing on pGSDMD and its function against pathogenic infection were rare." (PMID 35012343, 2022). "In the same study, GSDMD cleavage was increased during infection of J774A.1 cells and of murine ceca by SpvC-deficient bacteria as compared to infection with wild-type S. Typhimurium." (PMID 35801644, 2022). "Mice lacking both GSDMD and MLKL (pyroptosis/necroptosis) were similarly susceptible to lethal infection as Gsdmd−/− mice." (PMID 34154417, 2021). "Consistent with this, ΔospC3 infection caused cleavage of GSDMD and maturation of IL‐18, which are hallmarks of pyroptosis, whereas ΔospD3 infection did not (Fig EV1B)." (PMID 32657447, 2020). "Together, these parameters describe the fundamental differences in GSDMD trafficking between neutrophils and macrophages that underlie neutrophil-specific functions during inflammasome signaling in infection and responses to sterile tissue damage." (PMID 32371889, 2020).
infection (continued). "Similarly, gasdermin-D (GSDMD)-deficient astrocytes display increased susceptibility to infection, although their LDH release remains unaffected, suggesting that pyroptosis is not required for viral restriction." (PMID 41641274, 2026). "This may be due to the increased expression of NLRP3, apoptosis-associated speck-like protein (ASC), caspase-1, and GSDMD associated with pyroptosis in the host upon infection." (PMID 39011036, 2024). "Consequently, we investigated the role of the GSDMD N-terminal fragment in colon epithelial cells in defense against pathogenic infections." (PMID 38807373, 2024). "However, studies focusing on molecular mechanism of bovine Gasdermin D (bGSDMD)-mediated pyroptosis and its function against pathogenic infection were unclear." (PMID 38414065, 2024). "Indeed, 60% of WT mice succumbed to infection or met humane endpoint criteria of greater than 30% weight loss, compared to roughly 10% of Gsdmd−/− animals, demonstrating a protective effect when GSDMD is absent." (PMID 38553499, 2024). "For example, the inflammasome-associated caspases (CASP1/4/5/11) could directly cleave GSDMD and promote host defense against infection." (PMID 37528490, 2023). "Hence, in the background of an overall GSDMD-deficient tissue, individual GSDMD-expressing BM-derived cells fail to keep the infection at bay." (PMID 37988464, 2023). "Overall, our results suggest that NLRP3/GSDMD pathway mediated-pyroptosis in the lungs may be a key event in this process and provide new insights into the underlying mechanism of infection." (PMID 35761358, 2022). "GSDMD deficiency decreases the number of PI-positive cells after the infection." (PMID 36311722, 2022). "Although the increased proportion of macrophages did not depend on GSDMD in both spleen and peritoneal lavage fluid (PLF), deficiency of GSDMD caused the minor release of the pro-inflammatory cytokines interleukin-1β (IL-1β) and interleukin-18 (IL-18) during the infection in vivo." (PMID 36311722, 2022). "In contrast, GSDMD deficiency would inhibit the release of IL-1β and IL-18 after the infection." (PMID 36311722, 2022). "Additionally, GSDMD deficiency led to significantly less LC3 puncta formation at 6 h post-infection." (PMID 33441602, 2021). "However, inhibition of the receptor-proximal signaling kinases TAK1 or IKK by chemotherapeutic drugs or during infection by bacterial pathogens such as Yersinia, can trigger a caspase-8-dependent apoptosis pathway that is also associated with GSDMD cleavage." (PMID 34648590, 2021). "We observed that mice deficient in caspase-11 and GSDMD that are involved in pyroptosis are more susceptible to Brucella infection compared to wild-type animals, suggesting that B. abortus triggers pyroptosis and this event is important to control infection." (PMID 30589883, 2018). "Moreover, Gasdermin D-deficient mice were susceptible to intraperitoneal bacterial infection, with serious damage to the spleen and reduced secretion of cytokines IL-1β and IL-18 during in vivo infection." (PMID 36761775, 2023). "To analyze the role of caspase-1, caspase-11 and GSDMD in controlling B. abortus infection, we infected knockout (KO) mice for these molecules and we observed that caspase-11 and GSDMD KO animals were more susceptible to infection compared to wild-type animals." (PMID 30589883, 2018). "Similar to the NAIP/NLRC4 inflammasome, GSDMD is required for the protection against infection of IECs at 18 h post infection." (PMID 40796289, 2025). "In contrast, CASP1 and Gasdermin D (GSDMD) expression remains unchanged during the eclipse period of infection but increased significantly at 24 h.p.i." (PMID 40934228, 2025). "We also found that cleavage levels of GSDMD increased in response to both higher viral titers and longer infection durations." (PMID 40539222, 2025).
infection (continued). "Consistently, G. parasuis infection significantly up-regulated NLRP3, GSDMD, and caspase-1 expression at 24 h post-infection (hpi), indicating activation of the canonical pyroptotic pathway in PAMs." (PMID 40665414, 2025). "RS218 infection triggered robust pyroptotic responses, including increased expression of IL-1β and GSDMD, enhanced GSDMD cleavage to its active N-terminal form, activation of caspase-1 and its cleavage into the p20 subunit, and elevated IL-1β secretion." (PMID 40821830, 2025). "For example, studies employing wild-type S. Tm infections showed that the epithelial NAIP/NLRC4 inflammasome and downstream effectors (e.g., GSDMD) are crucial for preventing destructive inflammation in 72 h S. TmWT infection." (PMID 41370284, 2025). "Although GSDMD-mediated pyroptosis protects against pathogens’ infections, aberrant activation of GSDMD can trigger detrimental inflammatory cascades, such as cell lysis and the sustained release of inflammatory cytokines." (PMID 41305513, 2025). "We have previously shown that infection of human bronchial epithelial cells with IAV results in GSDMD cleavage and activation." (PMID 40481027, 2025). "The parasite interferes with GSDMD activation, inhibiting pyroptosis and allowing its survival within macrophages, thus contributing to the persistence of the infection in the host." (PMID 40431153, 2025). "Macrophage cell cytotoxicity was investigated by quantifying the release of lactate dehydrogenase during infection and by determining cleavage of the proinflammatory markers caspase-1, gasdermin D, and prointerleukin-1β." (PMID 40037395, 2025). "Western Blot showed that after 26695 infection, the pyropotosis marker cleaved Gasdermin D and apoptosis marker cleaved PARP were stronger than control, even also stronger than 5-FU treated alone." (PMID 39744419, 2025). "During infection activation of inflammasome sensor NLRP3 leads to cleavage of gasdermin D (GSDMD) induing pyroptosis, releasing IL-1β and IL-18 leading to further cytokine production." (PMID 40242761, 2025). "Consistently, we also observed cleavage of GSDMD upon infection with these viruses, which suggested that the protective function observed in GSDMD deficiency was due to the absence of GSDMD cleavage fragments." (PMID 40539222, 2025). "Our findings revealed that H37Rv infection led to a slight decrease in the N-terminal fragment of GSDMD and cleaved caspase-1, suggesting a subtle inhibition of pyroptosis." (PMID 40738187, 2025). "Lastly, targeting of GSDME alone, or in combination with GSDMD, significantly limited infectious virus release at 24 h following both Brazil/78 and HKx31 infection." (PMID 40481027, 2025). "Infection of primed murine neutrophils with Y. pseudotuberculosis ΔyopM resulted in activation of the pyrin inflammasome, GSDMD pore formation, IL-1β release and pyroptosis." (PMID 39883598, 2025). "Caspase-3-mediated inactivation of GSDMD was also rapidly observed following Brazil/78 and HKx31 infection, with the inactive p43 subunit strongly detected in cell lysates at 12 or 18 h, respectively." (PMID 40481027, 2025). "The findings highlight the role of GSDMD‐CT in inhibiting antiviral immunity, providing insights into how viruses manipulate host defense mechanisms to enhance infection." (PMID 40539222, 2025). "GSDMD activation succeeded GSDME activation, with the p30 subunit of GSDMD, as well as caspase-1 cleavage, observed in the cell supernatants from 18 h or 36 h following Brazil/78 and HKx31 infection." (PMID 40481027, 2025). "Further experiments in HepG2 cells showed that with the Adv‐Nrf2 infection titer increases, the expression of GSDMD mRNA and protein decreases." (PMID 39995148, 2025). "Corroborating these results, we observed that release of neutrophil elastase and myeloperoxidase into the cell supernatants following infection was largely dependent on GSDMD." (PMID 38553499, 2024).